RNU6-97P (RNA, U6 small nuclear 97, pseudogene)
Gene: Small nuclear RNA gene on chromosome 17 (76,752,912 to 76,753,015, forward strand). Ensembl gene ENSG00000200257.
Homologues: Orthologues: chimpanzee U6 (100% identical), rabbit U6 (96% identical), guinea pig U6 (93% identical), pig U6 (93% identical), guinea pig U6 (92% identical), mouse Gm22308 (92% identical), guinea pig U6 (91% identical), guinea pig U6 (90% identical), dog U6 (89% identical), guinea pig U6 (89% identical), rat LOC120095350 (85% identical), rat LOC120097654 (85% identical), and 2 more. Paralogues in human: RNU6-11P (94% identical), RNU6-37P (94% identical), RNU6-43P (94% identical), RNU6-25P (93% identical), RNU6-1 (92% identical), RNU6-15P (92% identical), RNU6-2 (92% identical), RNU6-28P (92% identical), RNU6-3P (92% identical), RNU6-492P (92% identical), RNU6-4P (92% identical), RNU6-5P (92% identical), and 1289 more.